CREB1 (cAMP responsive element binding protein 1)
Diseases named in the same sentence as CREB1 in open-access papers (continued):
Sharing a sentence is not in itself a finding about the gene and the disease.
glioma (72 papers, 2012 to 2026). A benign or malignant brain and spinal cord tumor that arises from glial cells (astrocytes, oligodendrocytes, ependymal cells). "Another study using the U87 glioma cell line identified GLUT1 as a key target gene regulated by CREB1 (cAMP-responsive element-binding protein 1) that has been implicated in many cancers." (PMID 40563757, 2025). "Then, we depleted the expression level of CREB1 and found the CREB1 downregulation caused an increase in the radiosensitivity of glioma cells." (PMID 34159190, 2021). "In general, whether our data are in contrast to other solid tumors (e.g. esophageal squamous-cell carcinoma, glioma), in which CREB1 expression and activation was associated with higher TNM stage and grading, needs to be discussed." (PMID 32300145, 2020). "Cyclic AMP-responsive element-binding protein 1 (CREB1) is a TF commonly overexpressed in high-grade gliomas." (PMID 39606019, 2024). "CREB1 was also highly expressed in glioma tissues through the induction of oncogenic microRNA-23a expression and increased the growth survival of glioma cells and colorectal cancer." (PMID 33921660, 2021). "Dual-luciferase reporter analyses showed that H19 was transcriptionally activated by CREB1 in glioma cells after irradiation." (PMID 34159190, 2021). "In this study, we manifested by bioinformatics methods that CREB1 was a target gene downstream of miR-654-3p, which was proven to facilitate varying malignancies including glioma as a proto-oncogene transcription factor." (PMID 35096015, 2021). "CREB1 has also been found to be highly expressed in glioma tissues and enhanced glioma cell growth survival by inducing the expression of oncogenic microRNA-23a." (PMID 25825983, 2015). "It was further observed that both CREB1 and GLUT1 expression levels were significantly elevated in GBM compared to normal brain and WHO grade I, II and III glioma samples, with CREB1 positively influencing the transcriptional activity of GLUT1, thereby enhancing its expression." (PMID 40563757, 2025). "LINC01857 acts as an oncogene that promotes BC development by promoting H3K27Ac and CREB1 transcription, regulates glioma progression by modulating the miR-1281/TRIM65 pathway, promotes the proliferation of cancer cells by activating the PI3K/mTOR pathway, and facilitates the EMT process in DLBCL." (PMID 36168326, 2022). "In addition to reducing metastasis and cell proliferation in bladder cancer cells, it also reduces gastric cancer, esophageal cancer, and glioma by knocking down CREB1 gene levels in tumor cells." (PMID 33921660, 2021). "For example, lncRNA XIST inhibits the expression of miR-329-3p, and miR-329-3p downregulation provokes cell proliferation and invasiveness and the upregulation of cAMP responsive element binding protein 1 (CREB1) expression, thus inducing radioresistance in glioma patients." (PMID 34202078, 2021). "In conclusion, the present study verified that radiation-induced CREB1 directly activated H19 transcription and upregulated H19 participated in radioresistance regulation of glioma cells via several cellular process, including apoptosis and G2/M phase arrest and DNA synthesis." (PMID 34159190, 2021). "Their gain-of-function assays confirmed that up-regulation of miR-1224 displayed increased abilities of the invasion and growth of glioma cells by targeting CREB1 However, whether miR-1224 may display a similar in other tumors remains unclear." (PMID 34604093, 2021). "Consistently, CREB1 has also been identified to be highly expressed in glioma tissues and promote cell growth by activating the expression of oncogenic microRNA-23a, and plays an important role in the tumorigenesis of renal cancer by loss of tumor suppressive miR-10b-5p and miR-363-3p." (PMID 27801665, 2016). "Furthermore, it has been shown that the phosphorylation of CREB1 can be up-regulated by thapsigarine (ER stress inducer) in human glioma cells." (PMID 23339444, 2013).
glioma (continued). "In this study, we explored whether radiation-induced CREB1 directly activates H19 transcription, and then, the depletion of H19 reduced the radioresistance of glioma cells, aiming at providing a novel target for radiotherapeutic intervention against glioma." (PMID 34159190, 2021). "While these four genes (PDGFA, PDGFRA, CREB1, and PLAT) have been studied individually, our findings highlight their collective significance in glioma." (PMID 39606019, 2024). "Transcripts of VV-GMCSF-Lact-infected glioma and NB cells that directly correlate with CD50 are enriched with mRNAs controlled by transcription factors ATF2, BRCA1, CREB1, ELF1, TAF1, UBTF, and YY1." (PMID 37998351, 2023). "CREB1, as a cAMP response element binding protein-1, cooperated with AMPK and was involved in glioma cell proliferation." (PMID 36715873, 2023). "Pathway enrichment analysis identified four essential genes—PDGFA (ligand), PDGFRA (receptor), CREB1 (TF), and PLAT (target gene)—involved in the Receptor Tyrosine Kinases (RTK) signaling pathway, which plays a pivotal role in glioma progression from grade III to grade IV." (PMID 39606019, 2024).
hepatocellular carcinoma (66 papers, 2005 to 2026). A malignant tumor that arises from hepatocytes. "POLR2J4 functioned as an oncogene in colorectal through the microRNA-203a-3p.1 and CREB1 axis and is highly expressed in hepatocellular carcinomas." (PMID 36065303, 2022). "Furthermore, RUSC1-AS1 promotes development of hepatocellular carcinoma by modulating the miR-340-5p/CREB1 axis to affect the proliferation, invasion and migration abilities of cancer cells." (PMID 37400520, 2023). "Together, these results underscore the importance of iron, AMPK, CREB1 and GLUT3 pathways in cell proliferation and highlight the therapeutic potential of sodium beta-hydroxybutyrate in hepatocellular carcinoma with high GLUT3 expression." (PMID 38994998, 2024). "Similar findings were reported for CREB-1 and ATF-1 in human hepatocellular carcinoma cells and human leukemia cells." (PMID 21760912, 2011). "In hepatocellular carcinoma (HCC), enriched Bacteroidetes ovatus metabolizes chenodeoxycholic acid into isolithocholic acid to impair the cytotoxicity of hepatic NK cells in a phosphorylated CREB1-dependent manner, resulting in accelerated tumor progression." (PMID 40770084, 2025).
lung cancer (66 papers, 2010 to 2025). A malignant neoplasm involving the lung. "CREB1, a known oncogenic factor, has been implicated in several cancers, including colorectal cancer, cervical cancer, liver cancer, lung cancer, and so on." (PMID 40823777, 2025). "Similarly, increased expression of CREB1 has been associated with poor prognosis in lung cancer, and its suppression has been reported to be promising in treatment." (PMID 40283966, 2025). "Some DEGs were found to be involved in more than one main pathways like MAPK1 and CREB1 were found in viral carcinogenesis, adrenergic signalling and non‐small cell lung cancer." (PMID 39434198, 2024). "However, CREB1 phosphorylation contributes to cisplatin sensitivity in lung cancer cells via regulation of the ERK pathway, especially in cancer cells with mutated SET domain containing 2 (SETD2), a histone H3 lysine 36 (H3K36) trimethyltransferase." (PMID 38233872, 2024). "Collectively, the effect of PKA/CREB1 pathway may be subject to the different contexts in lung cancer." (PMID 37957645, 2023). "However, some studies recognized miR-182-5p as an inhibitor of the process of proliferation; indeed, miR-182-5p downregulates the mRNA products for proteins promoting the cancer development, including CTTN, RGS17, and CREB1 in ovarian papillary carcinoma, gastric adenocarcinoma, and in lung cancer." (PMID 36980984, 2023). "The levels of ATF1/CREB1 in immortalized epithelial (MCF-10A) and a panel of breast, colon and lung cancer cells indicate the presence of ATF1 in multiple cancer types." (PMID 37463926, 2023). "In the present study in lung cancer, LINC00152 knockdown leads to reduced several cell growth-related proteins such as STAT3, p38α, CREB1, STAT1, c-MYC and CCNE1." (PMID 28592840, 2017). "For example, GemiNI analysis of a lung cancer data set with paired gene/miRNA expression (GSE18805,) identified top TFs (CREB1, SP1 and STAT3) and miRNAs (miR-15a, miR-195 and miR-497) that are dysregulated in lung cancer." (PMID 23418540, 2013). "Based on our finding that LINC00152 was mainly located in the cytoplasmic of lung cancer cells, the regulation process targeted to p38α, STAT1, CREB1 and c-MYC growth related proteins may be at the post-transcriptional level such as protein degradation mechanism." (PMID 28592840, 2017).
Obesity (59 papers, 2009 to 2026). Accumulation of substantial excess body fat. "An in vivo study reported that Creb1 deficiency in the hypothalamus induces obesity by decreasing energy expenditure." (PMID 28170448, 2017). "We found that several serum leptin-associated genes including Peli3, Creb1, and Enpp2 and serum insulin-associated genes such as Centg1 are associated with obesity and colonic diseases." (PMID 28170448, 2017). "This study demonstrates that HIF-1α, a master regulator of oxygen homeostasis, stimulates PII-driven aromatase expression in human breast ASCs with other transcription factors, including CREB1, in response to tumor-derived and obesity-associated inflammatory mediator PGE2." (PMID 23566437, 2013). "The most significant process/pathways exclusively found in TNBC tumors of EA patients with obesity are involved mainly with CREB1, and RAS proteins There is documented evidence that CREB1 plays a role in promoting BC." (PMID 41009685, 2025). "CREB mediates the effects of canonical MC4R signalling through the Gαs–cAMP–PKA cascade, and mice with genetic deletion of Creb1 in Sim1 neurons develop obesity, impaired thermogenesis, and reduced AVP expression." (PMID 36175420, 2022). "We first compared the livers of lean and obese mice and found that both total and activated (phosphorylated) CREB1 (p-CREB1) were increased in obesity." (PMID 32657780, 2020). "Our data suggest Peli3, Creb1, Enpp2, and Centg1 as potential early biomarker candidates for obesity-induced pathophysiological changes in the colon." (PMID 28170448, 2017). "Nevertheless, the cyclic AMP (cAMP) responsive element-binding protein-1 (CREB1) is expressed in the VMH, and CREB1−/− mice exhibit adult onset obesity associated with hyperphagia, elevated insulin and leptin levels, as well as leptin resistance." (PMID 19750222, 2009). "Notably, we showed that circGlis3/miR-124-3p/NeuroD1 and Creb1 are involved in pathological changes in β-cells in response to obesity." (PMID 36681689, 2023). "In addition, CREB1 is proposed as an early biomarker candidate for obesity-induced pathophysiological changes in the colon." (PMID 33302351, 2020). "As LRP1 is abundant on the surface of hepatocytes, we hypothesized that PAI-1 activates CREB1 through LRP1-PKA–mediated signaling to increase tPA expression in obesity." (PMID 32657780, 2020). "Finally, CREB1 has been assessed as a non-pharmacological strategy against obesity and associated diseases." (PMID 39062927, 2024). "Reduced binding of the cyclic AMP responsive element binding protein-1 (CREB1) to the hypermethylated cyclic AMP response element, which is a regulatory element upstream of the transcription initiation site, partially contributed to the downregulation of FGF6 in patients with obesity." (PMID 34491915, 2021).
prostate carcinoma (59 papers, 2009 to 2026). A carcinoma that arises from epithelial cells of the prostate gland. "A previous study found that CREB1 and FoxA1 associated with advanced prostate cancer, and CREB1/FoxA1 target gene panels can predict prostate cancer recurrence." (PMID 30138363, 2018). "The minor allele of rs10993994 in the promoter of the MSMB gene has been associated with prostate cancer and it creates a cognate site that is bound by CREB1." (PMID 28186491, 2017). "We found that REST levels are reduced, while p-S133-CREB1 (an indicator of CREB1 activation) and NE markers are increased, when prostate cancer cells are treated with ISO or Fsk+IBMX." (PMID 38777812, 2024). "All these results together indicate that CREB1 signaling induces NE markers through repressing REST expression in prostate cancer cells." (PMID 38777812, 2024). "Numerous studies have established the promoting role of CREB1 in the carcinogenesis of multiple cancers, such as liver cancer, colorectal cancer, and prostate cancer." (PMID 37285335, 2023). "In prostate cancer cell lines, upregulation of miR-493-5p inhibited CREB1 expression and inhibited EMT via AKT/GSK-3β/Snail signaling." (PMID 34830370, 2021). "Induction of HDAC2 by CREB1 is critical for prostate cancer progression promoted by chronical bio-behavioral stress that activates PKA-CREB1 pathway though beta adrenergic signaling." (PMID 32039001, 2019). "Additionally, during the transition from normal prostate cells to prostate cancer cells, DNA demethylases (TETs) reduce DNA methylation levels in the promoter region of CtIP, facilitating the binding of CREB1 to the CtIP promoter." (PMID 41912484, 2026). "Except for directly targeting SLC7A11, miR-654-3p might suppress SLC7A11 transcription by targeting CREB1 in prostate cancer cells." (PMID 41228362, 2025). "To test this hypothesis, we first treated prostate cancer cells with known compounds that either enhance or inhibit CREB1 signaling, followed by examining REST and NE marker expression." (PMID 38777812, 2024). "Moreover, we found that REST cDNA overexpression in PC3 cells reversed NE marker induction by the activation of CREB1 signaling by Fsk+IBMX, which suggests that REST downregulation is essential for CREB1’s induction of NE markers in prostate cancer cells." (PMID 38777812, 2024). "Besides, in prostate cancer cells, abiraterone acetate treatment can induce CREB1 phosphorylation, which in turn enhances CBP/p300 activity and lead to alterations in global gene expression and subsequently drug resistance." (PMID 35769513, 2022). "We performed Transewell assays to identify the function of CREB1 in prostate cancer cell motility." (PMID 29137265, 2017). "EP300 and CREBBP, regulated by way of miR-30a and CREB1, are highly related transcriptional co-activators possessing histone acetyltransferase activity and were known to be involved in the survival and invasion pathways of prostate cancer." (PMID 23282077, 2012). "In summary, our study reveals that inhibition of the CREB1-CtIP axis effectively improves the therapeutic outcomes of Abi-RT combination therapy, which may offer a novel clinical strategy for the treatment of prostate cancer." (PMID 41912484, 2026). "Additionally, CREB1 involved in regulating EMT via VEGF signaling in prostate cancer." (PMID 29137265, 2017). "We conclude that in prostate cancer cells the proliferative signals are likely to be transmitted from multiple growth factor receptors by a multitude of signaling pathways converging on several key regulators of cell proliferation such as c-Myc, Cyclin D and CREB1." (PMID 20532174, 2010). "Here we confirmed this conclusion, by showing that expressing activated CREB1 cDNA (Y134F), or treatment of CREB1 signaling activator Forskolin or ISO, increases H3K27me3 epigenetic mark in LNCaP and PC3 prostate cancer cells." (PMID 38777812, 2024).
prostate carcinoma (continued). "To better understand the mechanisms of NED in prostate cancer cells, here we investigated the links between ADT, CREB1, EZH2, and REST." (PMID 38777812, 2024). "Our study provides evidence that CREB1 signaling represses REST mRNA and protein expression during neuroendocrine differentiation of prostate cancer cells." (PMID 38777812, 2024). "Treatment of prostate cancer cells with abiraterone acetate increases intracellular cAMP levels and PKA activity, leading to CREB1 phosphorylation that promotes abiraterone acetate resistance." (PMID 38233872, 2024). "We previously showed that ADT activates CREB1 signaling, which is critical for NED of prostate cancer cells." (PMID 38777812, 2024). "CREB1 is an oncogene that was shown to promote tumor cell proliferation, EMT transition, and metastasis in gastric cancer, CRC, and prostate cancer." (PMID 34830370, 2021). "We demonstrated novel regulatory circuits involving miR-493-5p, c-Met, CREB1 and EGFR that controlled prostate cancer progression." (PMID 29137265, 2017). "We examined decreased expression of CREB1 and EGFR in miR-493-5p-treated prostate cancer cells at both mRNA and protein level." (PMID 29137265, 2017). "Our study identified c-Met, CREB1, EGFR and miR-493-5p establish a regulatory loop in prostate cancer." (PMID 29137265, 2017). "Thus it is reasonable to conclude that in prostate cancer cells the proliferative signals are transmitted from growth factor receptors by a multitude of signaling pathways converging on several key regulators of cell proliferation such as c-Myc, Cyclin D and CREB1." (PMID 20532174, 2010). "Notably, ADT-activated CREB1 signaling enhances EZH2’s epigenetic repression of REST, which in turn induces NE markers in prostate cancer cells." (PMID 38777812, 2024). "Furthermore, we identified c-Met, CREB1, EGFR and miR-493-5p establish a regulatory loop in prostate cancer." (PMID 29137265, 2017). "Taken together, our study identified c-Met, CREB1, EGFR and miR-493-5p establish a regulatory loop in prostate cancer, which could prove useful in the development of effective and therapies against prostate cancer." (PMID 29137265, 2017).